LEF1 (lymphoid enhancer binding factor 1)
Diseases named in the same sentence as LEF1 in open-access papers (continued):
Sharing a sentence is not in itself a finding about the gene and the disease.
breast carcinoma (continued). "Further, we considered the well-known involvement of the LEF1/TCF family with thelymphatic and immune system to investigate its implication in immunologic subtypesand the abundance of immune infiltrates in breast cancer." (PMID 38100720, 2023). "Treatment with buparlisib (PI3Kα/β/δ/γ inhibitor) reduced the expression of Wnt target genes AXIN2, LEF1, and MYCN in human PIK3CA-mutant ER+ breast cancer cells." (PMID 37471270, 2023). "Our previous study showed that β-catenin translocated into the nucleus to form a transcription complex with TCF4 and LEF1, which then promotes FMOD transcription, subsequently leading to breast cancer cell migration and invasion." (PMID 36986805, 2023). "Besides, collagen type I could augment SNAI1- and LEF-1-mediated EMT in breast cancer." (PMID 36712590, 2023). "Among them were major regulators of breast cancer cell proliferation, including CCND1, LEF1, KLF9, GREB1, or MAP3K3." (PMID 36076907, 2022). "Increased DEK can then bind the LEF1 internal ribosome entry site sequence, thereby increasing the translation of the oncogenic LEF-1 mRNA and promoting the invasion and metastasis of breast cancer cells." (PMID 34975491, 2021). "LOC641518-lymphoid enhancer-binding factor 1 (LEF1) pair was selected to verify its role in migration and invasion capability of breast cancer cells by wounding healing assay and transwell invasion assay." (PMID 34256750, 2021). "In breast cancer, the single-cell profiling of docetaxel-resistant MCF7 breast cancer cells revealed a subset of cells with a stem-like phenotype and identified LEF1 as the critical molecule regulator in drug resistance." (PMID 34177965, 2021). "Our independent analysis of primary ER+PIK3CA-mutant breast cancers, which exhibit high INPP4B expression, identified these and additional upregulated Wnt genes (LEF1, MYCN, FZD7, SFRP2, TCF7L1, CTNNB1, FZD4, and SFRP1)." (PMID 34035258, 2021). "A recent report showed that LEF1 and multidrug resistance-related genes, such as ABCG2, VIM, and Cav1, are highly increased in docetaxel (DTX)-resistant MCF7 breast cancer cells, indicating that LEF1 is involved in multidrug resistance in cancer." (PMID 32933177, 2020). "Using lentivirus-mediated shRNA targeted for β-catenin, TCF4, and LEF1, we investigated the relation between endogenous β-catenin, TCF4, LEF1, ERK1/2 activity, and breast cancer cell migration and invasion." (PMID 31824307, 2019). "We find for the first time that in breast cancer cells FMOD expression is regulated positively by the Wnt/β-catenin signaling pathway, and FMOD is transcribed by the β-catenin/TCF4/LEF1 transcription complex which binds to the FMOD promoter at specific sites." (PMID 31824307, 2019). "To find the relevance of the NUMB, TCF7, and LEF1 promoters to β-catenin/RAC1, we performed a ChIP assay using anti-β-catenin/anti-RAC1 antibody in both colon and breast cancer chromatin samples." (PMID 30650643, 2019). "Hepatocyte growth factor (HGF) transcriptional activation of LEF1 was shown to be dependent on AKT/NF-κB signaling in liver and breast carcinoma cell lines." (PMID 29535816, 2018). "Our data show that SID peptide downregulates Wnt/β-catenin reporter activity and direct Wnt target genes (LEF1, TCF7L2, CD44, PLAU, MT1-MMP, MMP9, HMGA2) involved in breast cancer invasion and metastasis." (PMID 29179446, 2017). "LEF1 was found to be prominent in colon cancer and was also discovered in several types of MCF7 breast cancer." (PMID 28607444, 2017). "Confirming the results observed using cell lines we observed higher expression of LEF1, suggesting WNT activation in Luminal, ER+ve breast cancer patients." (PMID 23861811, 2013). "Notably, LEF1‐expressing CAFs are prevalent in the stroma of squamous cell carcinoma (SCC), an aggressive metaplastic breast cancer subtype with a limited understanding of its development." (PMID 39887653, 2025).
breast carcinoma (continued). "Additionally, the reported role in breast cancer of fetal mammary developmental genes, such as TBX3, WNT-10b, FGF10, and LEF1, highlights their potential clinical relevance as biomarkers and therapeutic targets." (PMID 40001874, 2025). "TCF/LEF1, a key transcription factor in canonical Wnt/β‐catenin signaling pathway, is overexpressed in HER‐2 negative breast cancers and has been implicated in brain metastasis through modulation of glutathione metabolism and ROS resistance." (PMID 41306556, 2025). "DCIS.com breast cancer cells were combined with the exp‐CAFs with or without LEF1 knockdown and injected subcutaneously." (PMID 39887653, 2025). "Our findings suggest that aberrant LEF1 expression in CAFs may drive tumor proliferation and contribute to the transdifferentiation process toward SCC in breast cancer." (PMID 39887653, 2025). "In addition, FMOD is critical for breast cancer cell migration and invasion and is positively regulated by the β-catenin/TCF4/LEF1 complex." (PMID 36986805, 2023). "PIK3CA mutant ER+ breast cancers exhibit an RNA expression profile of enhanced Wnt/β-catenin signaling, including up-regulation of Wnt target genes (AXIN2, LEF1, MYCN) and other components such as transcriptional regulators (TCF7L1, TCF7L2, CTNNB1), receptors (FZD4, FZD7) and ligands (WNT5A)." (PMID 37471270, 2023). "We also examined the expression of these genes in a separate cohort of 698 luminal (ER/PR+) breast cancers using the TCGA dataset, where PIK3CA-mutant cancers displayed significantly higher expression of eight Wnt genes (LEF1, TCF7L1, TCF7L2, CTNNB1, LRP6, SFRP2, WNT5A, and MSX2)." (PMID 34035258, 2021). "Similarly, nuclear β-catenin expression and increased LEF1 levels are reported in migratory, vimentin-expressing oral squamous cancer cells (OSCC) and breast cancer cells." (PMID 34638929, 2021). "Current study identified that LOC641518 cis-regulated the expression of LEF1 in group of bone metastasis vs lung metastasis, which might indicate that LOC641518 involved in breast cancer bone metastasis through regulating LEF1." (PMID 34256750, 2021). "In breast cancer cells, knockout of TMEM97 attenuated the Wnt/β-catenin signaling cascade via regulating LRP6 phosphorylation, leading to a decrease in the expression of Wnt target genes AXIN2, LEF1, and survivin." (PMID 34615853, 2021). "Increased mRNA expression of AXIN2 (1.9-fold), LEF1 (2.3-fold), and DKK1 (3.2-fold) was also observed in T47D cells expressing GFP-INPP4B, demonstrating that INPP4B enhances Wnt/β-catenin signaling in PIK3CA-mutant ER+ breast cancer cells." (PMID 34035258, 2021). "Although Lef1 expression has not been found to be significant in breast cancer, our laboratory has recently reported a novel role for Lef1 in breast cancer drug resistance." (PMID 32492961, 2020). "At first, we examined the expression of Wnt/β-catenin signaling-related genes and found that expression levels of CTNNB1, LEF1, and TCF genes were significantly downregulated both in colon and breast cancers, which was confirmed by a TOP-/FOP-Flash reporter assay." (PMID 30650643, 2019). "Partner enzymes in U34 tRNA modification, including ELP3 and CTU1/2 were found to be up-regulated in human breast cancers and sustain metastasis, through the translation of the oncoprotein DEK, that promotes the translation of the pro-invasive transcription factor LEF1." (PMID 31238876, 2019). "Elevated basal, ligand-independent, Wnt signaling in some canine breast cancer cells is not caused by classical mutations in APC, β-Catenin or GSK3β but, at least partially, by enhanced LEF1 expression." (PMID 26205886, 2015). "Analysis of additional markers of EMT revealed that breast cancer samples with high PEAK1 levels expressed reduced levels of the epithelial markers MUC1, E-Cadherin and Entactin and increased levels of the mesenchymal markers Syndecan1 and LEF1." (PMID 26267863, 2015).
breast carcinoma (continued). "There was also a considerable increase in the expression of others genes described as stem cell markers and expressed in CD44high fractions of normal and breast cancer tissues, including FOXC1(∼11-fold), IGFBP7 (∼8.5-fold), PROCR (∼8.2-fold), LEF1 (∼6.7-fold) and ZEB1 (∼6.6-fold)." (PMID 24498388, 2014). "Independent of ER status, overall WNT pathway signalling assessed by the canonical downstream target genes AXIN2 and LEF1 is higher in breast cancer cell lines compared to normal breast cell lines." (PMID 23861811, 2013). "Consistent with its gene expression level, LEF1 protein was higher in five breast cancer cell lines compared to two normal cell lines (MCF10A and 226LU19), providing further evidence that WNT signalling is active in breast cancer cell lines." (PMID 23861811, 2013). "However, Lef1 overexpression has not been described as a common phenomenon in Luminal subtype of breast cancer tissue; according to our prior data less than 10% of tumors presented high amount of Lef1 expressing cells." (PMID 32492961, 2020). "Lymphoid enhancer-binding factor 1 (LEF1) is a key downstream mediator of the activated Wnt/ β-catenin signaling pathway, which regulates tumorigenesis and the progression of multiple tumours, such as breast cancer, lung adenocarcinoma, colon cancer, prostate cancer and leukemia 5-9." (PMID 32226522, 2020). "Likewise, LiCl enhanced breast cancer cell motility; but the enhancement could be eliminated by knocking down FMOD, or individual components of the β-cat/TCF4/LEF1 transcriptional complex, or by inhibiting HDAC6 with Trichostatin A (TSA)." (PMID 31824307, 2019). "Likewise, LEF1 and STAT5 related genes were highly expressed in ibuprofen treated myeloid cells and highly correlated with better outcomes in the TCGA primary breast cancer data set." (PMID 30285905, 2018). "Furthermore, expression of neither c-Myc, CCND1, nor LEF1 differed in TCGA breast cancer tumours with wild-type versus mutant RUNX1." (PMID 26916619, 2016). "However, it could also be β-catenin-independent LEF1 or WNT functions, as suggested for the latter in breast cancer brain metastasis." (PMID 23224985, 2013). "In contrast, LEF1 was able to regulate MMP-7 expression and activity in breast cancer cells, whereas another previous study showed that circulating MMP-2 and MMP-9 could be used to potentially classify patients into low risk, high risk, benign disease, and breast cancer." (PMID 24098538, 2013). "The role of necroptosis-related genes in breast cancer, such as FASLG, FLT3, HSPA4, IDH2, IPMK, LEF1, and SLC39A7, has not been extensively studied, and these necroptosis-related genes have been confirmed to regulate the biological processes of necroptosis in various types of tumors." (PMID 36675706, 2022).
melanoma (48 papers, 2012 to 2025). A malignant, usually aggressive tumor composed of atypical, neoplastic melanocytes. "In melanoma, increased cell proliferation and invasion has been associated with the lower miR-708 targeting of Lymphoid Enhancer-binding Factor-1 (LEF1), which is a member of the Wnt pathway." (PMID 35011736, 2022). "Here, we show that LEF1 is highly expressed in cultured melanoma cells and that melanoma cells expressing high levels of LEF1 are susceptible to LEF1 suppression." (PMID 32933177, 2020). "It was observed that the increase in TCF4 and decrease in LEF1 was associated with an invasive transformation of melanoma, in contrast with epithelial tumors where the upregulation of beta-catenin interaction factor LEF1 was seen to promote EMT." (PMID 31934531, 2019). "LEF1 is an outstanding candidate gene for melanoma susceptibility as it can regulate microphthalmia-associated transcription factor, KIT-ligand (KITLG), tyrosinase, and other melanogenic genes." (PMID 30744341, 2019). "Both MITF and LEF1 have been implicated in melanoma survival and resistance." (PMID 33647315, 2021). "Here, we used a cell viability assay to understand whether LEF1 expression is associated with proliferative potential in cultured melanoma cells." (PMID 32933177, 2020). "It has been demonstrated that silencing of LEF1 in melanoma cells triggers phenotypic changes commonly known as “phenotype switching”." (PMID 40943659, 2025). "A recent study confirmed the role of IGF2BP2 in melanoma development through the MSC-AS1/miR-302a-3p/IGF2BP2/LEF1 axis." (PMID 40211852, 2025). "Because endogenous levels of LEF1 mRNA and protein were also detectable in several melanoma cells, we silenced LEF1 expression in a repertoire of melanoma cells using a specific siRNA." (PMID 40943659, 2025). "Using IHC, DPN and DPN-like melanomas both express β-catenin (cytoplasmic and membranous), cyclinD1 (nuclear and cytoplasmic), and LEF1." (PMID 38247727, 2024). "Uniform strong nuclear staining with β-catenin and/or LEF1 IHCs suggests the diagnosis of DPN or DPN-like melanomas, confirming the altered Wnt/β-catenin pathway that is distinct in this group of lesions." (PMID 38247727, 2024). "The target genes with binding sites for LEF1 and TEAD are involved in rRNA processing and are associated with poor prognosis in melanoma patients." (PMID 38388496, 2024). "As mentioned in the previous section, DPN and DPN-like melanomas both express β-catenin, cyclinD1, and LEF1 due to the shared Wnt/β-catenin pathway alteration." (PMID 38247727, 2024). "Our findings revealed a significantly elevated expression of LEF1 in various tumors compared with normal tissues, including melanoma, thymic cancer, and colorectal cancer." (PMID 37657935, 2023). "The same study showed that loss of LEF1 and gain of TCF4 expression was associated with melanoma progression, involving changing from a proliferative to an invasive phenotype." (PMID 36675114, 2023). "Differentiated/proliferative phenotype melanoma cells preferentially express LEF1 and dedifferentiated/invasive phenotype cells usually express TCF4." (PMID 36675114, 2023). "MITF expression is modulated through β-catenin and another key effector in the Wnt pathway called lymphoid enhancer-binding factor 1 (LEF1) in melanoma cells." (PMID 33647315, 2021). "CD8+ T-cell-restricted Lef1 ablation resulted in uncontrolled ovarian, melanoma and NBL tumor growth." (PMID 34721405, 2021). "Our data establish that LEF-1 and IL-21R are necessary for the optimal control of ovarian, melanoma and NBL tumor growth." (PMID 34721405, 2021). "We generated LEF1 silenced melanoma cells using short hairpin RNA (shRNA) to understand the functional role of LEF1 on melanoma cell growth and observed decreased LEF1 protein levels in LEF1 knocked-down A375, A2058, and G361 cells." (PMID 32933177, 2020).
melanoma (continued). "Cinobufagin decreases LEF1 expression in a dose-dependent manner and Wnt/β-catenin target genes such as Axin-2, cyclin D1, and c-Myc in melanoma cell lines." (PMID 32933177, 2020). "In this screening, we found that the natural compound, cinobufagin, was a potent inhibitor of canonical Wnt/β-catenin signaling, decreasing LEF1 expression and consequently suppressing melanoma growth and inducing apoptosis." (PMID 32933177, 2020). "Although it is well known that LEF1 usually involves melanocyte differentiation and phenotype switching by increasing microphthalmia-associated transcription factor (MITF), the pro-survival role of LEF1 in melanoma is not fully understood." (PMID 32933177, 2020). "While A375, A2058, and G361 melanoma cells exhibit abnormally high LEF1 expression, lung cancer cells express lower LEF1 levels." (PMID 32933177, 2020). "Emerging evidence has shown that Lymphoid enhancer-binding factor 1 (LEF1) expression is highly increased in leukemia and various types of solid cancer, such as lung adenocarcinoma, colorectal cancer, prostate cancer, and malignant melanoma." (PMID 32933177, 2020). "Cinobufagin was found to decrease LEF1 expression in A375, A2058, and G361 melanoma cells in a dose-dependent manner." (PMID 32933177, 2020). "Here, the major finding is that cinobufagin suppresses melanoma cell growth and induces apoptosis by inhibiting the LEF1-mediated Wnt/β-catenin signaling pathway." (PMID 32933177, 2020). "Surprisingly, highly increased nuclear LEF1 levels were observed in A375, A2058, and G361 melanoma cells, but increased nuclear LEF1 was only detected in H1299 cells among nine lung cancer cell lines." (PMID 32933177, 2020). "Consistently, decreased cell viability in cinobufagin-treated A375 and A2058 melanoma cells was reversed by ectopic LEF1 expression." (PMID 32933177, 2020). "Here, we demonstrate that cinobufagin has an anti-melanoma effect by decreasing LEF1 and Wnt/β-catenin signaling." (PMID 32933177, 2020). "Cinobufagin sensitively attenuates cell viability and induces apoptosis in LEF1 expressing melanoma cells compared to LEF1-low expressing lung cancer cells." (PMID 32933177, 2020). "Overexpression of miR-708 inhibits the proliferation, invasion, migration, and epithelial-mesenchymal transition but also promotes the apoptosis of melanoma cells by targeting LEF1 through suppression of the Wnt signaling pathway." (PMID 31753039, 2019). "AZD6244-BEZ235, but not PLX4720-BEZ235, downmodulated the anti-apoptotic gene Bcl-2 and the mTOR interactor 4EBP1, as well as β catenin, a gene that impairs T cell-mediated immune response in melanoma, and LEF-1 a β catenin interacting partner." (PMID 26678033, 2016). "MITF-M is one of the LEF1/β-catenin target genes that is specifically expressed in melanocytes and melanoma cells." (PMID 27351373, 2016). "It has already been shown that the expression of TCF4 and LEF1 is inversely correlated in melanoma, and LEF1 suppresses TCF4 expression in a β-catenin-independent manner." (PMID 27351373, 2016). "In contrast to β-catenin, a phenotype-specific expression of LEF1 has been shown in melanoma cells limiting LEF1/β-catenin-dependent MITF transcription to a defined cellular context." (PMID 25433395, 2015). "LEF1 expression is predominantly observed in melanoma cell lines with high migration capacity, possibly acting through epithelial-mesenchymal transition." (PMID 24098529, 2013). "The majority (except FOXC1 and LEF1) was also found upregulated in the SP of the melanoma cell line." (PMID 24098529, 2013). "Aberrant overexpression of the Wnt-pathway target gene LEF1 has been detected in several cancers, principally: colon, leukemia, melanoma, and pancreatic." (PMID 22792274, 2012). "A study showed that the proliferation and invasion of the melanoma cell is regulated by LEF1/TCF activity." (PMID 22950635, 2012).